TLR9 (toll like receptor 9)
Diseases named in the same sentence as TLR9 in open-access papers (continued):
Sharing a sentence is not in itself a finding about the gene and the disease.
infection (continued). "TLR9 is involved in the recognition of H. pylori DNA but is the only TLR with an anti- and pro-inflammatory action and it could be able to promote or suppress the infection with H. pylori according to the gastric environment." (PMID 40362298, 2025). "TLR9 is predominantly expressed on mucosal epithelial cells, dendritic cells, macrophages, and other immune cells, where it plays a critical role in the antiviral immune response against HSV-1, particularly during the early infection phase and within the trigeminal ganglia." (PMID 40534865, 2025). "Considering the known pathogenesis of SFTS and the potential role of mtDNA as an endogenous ligand and TLR9 stimulus, we further demonstrated that the mtDNA-TLR9 pathway is involved in exacerbating B cell differentiation into plasmablasts and promoting SFTSV infection." (PMID 40366175, 2025). "-Phage-encoded in the M1T1 clone.-Cleaves DNA in neutrophil extracellular traps (NETs).-Suppresses TLR9-mediated IFN-α and TNF-α production, leading to decreased macrophage bactericidal activity.-Weakens the recruitment of dendritic cells by reducing IFN-1 levels at the site of infection." (PMID 38258026, 2024). "Deletion of TLR9, however, did not attenuate IL10 induction after infection with S. epidermidis 1457, while being associated with a significantly increased IL10 expression after infection with 1457-M10 and 1457ΔatlE." (PMID 39567551, 2024). "The expression of the tlr2, tlr9, nod1 and nod2 receptors in the gills did not change significantly after bacterial exposure when compared to controls (0 h), although a tendency to decreased tlr2 expression was seen at 6 and 24 h post-infection." (PMID 37731496, 2023). "Finally, because early viral restriction was Mtb-infection dose-dependent, we explored whether suppression of viral replication in Mtb-infected mice was mediated through mycobacterial sensing by TLR2 or TLR9." (PMID 37720210, 2023). "Similarly to our results, TL2 and TLR4 mRNA expression in the ileum was upregulated in CV pigs 24 h after infection with S. Typhimurium, but TLR9 mRNA expression was not influenced." (PMID 38003758, 2023). "This implies that the ability to degrade TLR9 may serve an additional function during the viral life cycle, independent of initial infection." (PMID 35311536, 2022). "Therefore, we evaluated aspects related to a Th2/allergic immune response in the presence or absence of TLR9 during experimental infection with C. gattii." (PMID 36145419, 2022). "Although TLR9 is a known pro-inflammatory receptor in immune cells, in non-immune cells, including neurons, TLR9 may play a role in energy metabolism to protect cells during infection." (PMID 35911725, 2022). "However, agonist treatment together with Δrgg3 infection resulted in decreased TNF-α production in response to lipopolysaccharide (LPS; TLR4), heat-killed Listeria monocytogenes (HKLM; TLR2), and CpG oligodeoxynucleotide (ODN1826; TLR9)." (PMID 33947757, 2021). "Moreover, in an infection model for the DNA virus mouse Cytomegalovirus, the DNA sensor TLR9 only shows an effect in livers but not in spleens, clearly indicating an organ-specific effect." (PMID 34824277, 2021). "Also in the early infection stage, prior to complications it could be imagined that activation of TLR pathways including TLR9 could aid in fast and effective viral clearance especially in immunocompromised patients." (PMID 33519463, 2020). "The reduction of TLR9 expression in HHV-6A infected NK cells leads to an impaired cytokine expression that might prevent NK cells activation toward target cells and slow down the inflammatory response needed to fight the infection." (PMID 32140147, 2020).
infection (continued). "Given that HSV-2 in our current study was propagated in ME-180, the cell line also used for the subsequent infection experiments, the cytokine composition induced in the infection experiments would be similar to that in the viral stock and unlikely to impact TLR9 expression." (PMID 32194565, 2020). "TLR2, but not TLR9, was important for preventing S. aureus outgrowth during craniotomy infection, as revealed by the elevated bacterial burden in the brain, galea, and bone flap of TLR2 KO mice concomitant with global reductions in pro-inflammatory mediator production compared to WT animals." (PMID 32290861, 2020). "This process involves the CD8α+ DCs, which through TLR9-dependent recognition of the mtDNA (released from dead neutrophils) release IL-12p70, which generates FoxP3+Tregs from conventional CD4+T cells during a high dose infection, whereas a low dose infection induces CD8+T cell generation." (PMID 33643304, 2020). "As components of Gram-negative bacteria, LPS and CpG-ODN trigger TLR4 and TLR9 at the site of infection, respectively, although the biological effects of these two components may change at different stages of infection." (PMID 32397173, 2020). "In order to determine whether TLR9 was being upregulated only in infected macrophages or also in non-infected cells, we infected bone marrow derived macrophages (BMDMs) for 24 or 48h with H1N1 or mock infection." (PMID 30682165, 2019). "Interestingly, direct infection of isolated alveolar macrophages with PR8 also shows an increase in TLR9, TLR7 and TLR3, with no changes in TLR2, and reduced TLR4." (PMID 30682165, 2019). "Furthermore, IFN-γ levels in the BALF of TLR9-/- mice after IAV-SPS3 infection were not significantly higher than in dual-infected WT mice." (PMID 30682165, 2019). "However, care should be taken to know the nature of the secondary infection as TLR9 regulates MRSA, but not SPS3 coinfection." (PMID 30682165, 2019). "Interestingly, if the animals lacked both, TLR2 and TLR9 all animals died after infection pointing out the relevance of these receptors in HSV infection." (PMID 31114761, 2019). "Studies utilising TLR9−/− mice infected with L. major showed similar disease kinetics to those reported here with TLR2−/− and TLR4−/− mice, with increased lesion sizes and parasite burdens during the acute phase of infection with eventual control of the disease." (PMID 27716391, 2016). "Further examination of the endosomal TLR pathway using ODN 2088, an antagonist of the endosomal TLR7/8/9 pathways, implied that while TLR7 and TLR9 were each upregulated versus mock infection with either UV-inactivated or live RSV neither played a role in the IFN-β or IDO expression we observed." (PMID 27695127, 2016). "To that end, we stimulated different TLRs with their known ligands (e.g. TLR2 was stimulated with Pam3Csk4; TLR4 was stimulated with LPS, TLR7 was stimulated with imiquimod and TLR9 was stimulated with CpG-DNA) in the presence or absence of stimulation with Rv2463 or infection with M. tb H37Rv." (PMID 25915405, 2015). "Besides, we also observed that the spent media obtained from CpG-ODN (CpG-SM) or Poly(I:C)LL (Poly-SM) stimulated End1/E6E7 cells enhanced chemotaxis of U937 cells, suggesting involvement of TLR9 and RIG-I in the recruiting immune cells to the site of infection." (PMID 24409285, 2014). "Therefore, a high neutrophil recruitment to the site of infection appears to be responsible for the death observed in the absence of TLR9 during the early stages of P. brasiliensis infection." (PMID 23936560, 2013). "We also studied IFN-α production following infection of PBMCs with HSV-1, a virus largely spread among the adult population, as representative of DNA virus and compared IFN-α production with those obtained by triggering two TLRs reported as crucial for immunity to HSV-1, TLR9 and TLR3." (PMID 22768144, 2012).
infection (continued). "In line with this, the immunoregulatory role for TLR2 reported during the acute infection could be explained by the fact that the suppressive function of Tregs is directly controlled by the triggering of TLR2 but not TLR4 or TLR9." (PMID 21869919, 2012). "Here we tested whether in the absence of TLR9 signaling this enhanced resistance to infection develops with a delay, like sensitization to LPS." (PMID 22745710, 2012). "Thus, we conclude that neither reduced production of Th1 cytokines nor increased production of Th2 cytokines in response to infection can explain the enhanced exacerbation of fibrosis noted in TLR-9-/- mice." (PMID 21810214, 2011). "Interestingly, although mice simultaneously lacking TLR2 and TLR9 are highly vulnerable to infection, their mortality rate is still less than that of Myd88−/− mice, pointing to the involvement of other TLRs and/or IL-1/IL-18 in the control of mortality." (PMID 20442858, 2010). "Mice lacking TLR9 or MyD88 were capable of controlling HSV-1 replication after local infection." (PMID 19025601, 2008). "Thus, TLR-9 activation might not be essential in virulent infection but could play a crucial role in LdCen−/− vaccine-induced immunity." (PMID 37111420, 2023). "In fact, infections by parechovirus, an ssRNA virus, have already been shown to elevate the plasma IL-12p40 in young children, though it is not known whether this response is also mediated through TLR9." (PMID 35399111, 2022). "This suggests that RBIV is recognized by TLR9 to induce MHC class I expression for antigen processing and presentation during the early stage of infection, although RBIV might downregulate MHC-I and -II expression on RBIV-infected cells during the late phase of RBIV infection in rock bream." (PMID 32131541, 2020). "Moreover, the simultaneous absence of TLR7, TLR9, and TLR13 was associated with extreme susceptibility to infection, due to the inability of resident macrophages to produce chemokines and recruit neutrophils to infection sites." (PMID 32209688, 2020). "However, none of these infection parameters was reduced in vaccinated Tlr9−/− mice." (PMID 29896197, 2018). "Infection at delivery, but not earlier in pregnancy, was associated with significantly higher TLR3-mediated IL-6 and IL-10 responses in the first 3 months of life, and with significantly higher TLR3-/TLR7/8-/TLR9-mediated TNF-α and TLR9-mediated IL-10 responses at 6 or 12 months of age." (PMID 26580401, 2015). "However, unexpectedly, 40% of mice lacking TLR9 resisted to death up to 8 days post-infection." (PMID 24595157, 2014). "Given that WT, but not TLR-9-/- mice exhibited increased numbers of ileal FOXP3+ cells upon infection, reduced Treg numbers might be indicative for compromised ileal mucosal regulatory properties in the absence of TLR-9, which in turn contributes to a more devastating inflammatory scenario." (PMID 24932221, 2014). "Since the vertebrate immune system relies on non-methylated CpG recognition as a sign of infection and the observed CpG under-representation is present only in vertebrate viruses, it is reasonable to suggest that a similar mechanism with TLR9 could be used in RNA viruses." (PMID 23028561, 2012). "In addition, we found abrogation – or almost complete suppression – of infection by pseudoviruses containing the BaL or BR envelope glycoproteins in MDMs stimulated through TLR3 or TLR4, with only partial reduction observed in cells stimulated through TLR2, TLR7 or TLR9." (PMID 23028330, 2012). "Louse infection grade showed highly significant negative association with TLR2 responses to HKLM (LMM, F1,81.1 = 18.90; P < 0.001) and zymosan (LMM, F1,75.0 = 9.54; P = 0.003), TLR9 response (LMM, F1,80.6 = 7.20; P = 0.009) and TIR (LMM, F1,80.7 = 17.03; P < 0.001)." (PMID 19386086, 2009).
infection (continued). "Regarding the Y strain infections, independently of the presence/absence of SLAMF1, there are five GO terms shared, like the positive regulation of TLR7 and TLR9 signaling pathways and the alpha–beta T cell activation." (PMID 39000601, 2024). "As the role of M. hominis in the modulation of Rab7, TLR9, and CD180 has not been reported, additional studies are necessary to elucidate the M. hominis–PHK interaction in the infection process." (PMID 36296238, 2022). "The MyD88-activating agonist CpG (TLR9 agonist), but not TRIF-activating Poly I:C (TLR3 agonist), protects against infection in a macrophage-dependent manner." (PMID 36439136, 2022). "This analysis revealed that all genotypes had increased osteoclastogenesis from infection; however, WT cells incurred significantly greater infection-induced osteoclastogenesis than did cells lacking TLR2, TLR9, or TLR2/9." (PMID 36226943, 2022). "In regard to GLY mediated protection, in the current study, GLY was unable to reduce the levels of RAGE and HMGB1 in the absence of TLR9, but significantly reduced TLR4 levels in TLR9KO corneas after infection." (PMID 36422579, 2022). "In the infection scenario, the combination—but not the products alone—was able to increase the expression of TLR7 and TLR9 genes." (PMID 35334820, 2022). "TLR2, TLR3, TLR9, and TLR13 expression patterns showed no significant variations in mRNA expression in koala PBMCs with a range of subtype infection profiles (KoRV-A only vs. KoRV-A with KoRV-B and/or -C)." (PMID 33915914, 2021). "iNOS induction in WT, TLR7-/-, TLR9-/-, and TRIF-/- Hoxb8 neutrophils after infection with A. phagocytophilum was not significantly different." (PMID 33747981, 2021). "TLR-9 RNA in both maternal and foetal placenta and TLR-8 in foetal placenta were not over-expressed at any time after Nc-Spain7 infection." (PMID 32552750, 2020). "In contrast, our in vivo data suggest that TLR2 and TLR9 are not crucial for placental inflammation, since the infection in pregnant TLR2−/− and TLR9−/− mice produced similar results to those found in the infected WT group." (PMID 28819109, 2017). "In macaques that were SIV-infected without concurrent TLR7 and TLR9 blockade we detected a robust and transient increase in plasma levels of IFN-α which peaked at day 11 post infection." (PMID 23935491, 2013). "Here, the infection with P. yoelii 17XL or 17XNL induced the expression of TLR2, but not TLR4 and TLR9, on murine macrophages in the present study." (PMID 22463100, 2012). "Furthermore, in a S. aureus craniotomy biofilm infection model, TLR2, but not TLR9, was critical for host bacterial containment through the caspase-1-mediated activation of IL-1β, which was reduced in the Tlr2−/− mice." (PMID 36226943, 2022). "However, co-inoculation with Tn5A7 resulted in enhanced clearance of WT infection in both TLR4-/- and TLR9-/- mice, indicating that neither TLR4 nor TLR9 signaling is required for differential recognition of kanamycin-propagated A. baumannii by the host." (PMID 32168364, 2020). "In contrast, TLR2, TLR4, and TLR9 play relatively minor roles with minimal or no impact on IFN-γ production by splenocytes, including DC, and the response of the respective KO mice to LVS infection is only modestly compromised." (PMID 32745117, 2020). "To examine infection-induced antibodies in this context, we transferred immune and non-immune serum into mice stimulated with TLR4 or TLR9 agonists, since Plasmodium infection can stimulate the innate immune system and pro-inflammatory cytokine production via these receptors." (PMID 30811498, 2019). "At peak-infection, more pDC produced IFN-α in response to TLR7 (p = 0.02) or TLR9 stimulation (p = 0.08), when compared to baseline hence, the ability of pDC to produce IFN-α was not diminished during early P. falciparum blood-stage infection." (PMID 28572564, 2017).
infection (continued). "Such activation is not uncommon in pathogen infection, and likely resulted from a combination of the presence of EcN PAMPs and OMV nanoscale avidity enhancement, possibly facilitated by the elevated TLR9 stimulation noted previously." (PMID 25426709, 2014). "Neutropenic TLR9-/- mice were not protected from intracerebral infection with 1 × 104 CFU E. coli K1 by pre-treatment with 100 μg CpG ODN (P = 0.10, log-rank test; survival 14 days after infection 8% (2/25, CpG group) versus 36% (9/25, buffer group)." (PMID 24456653, 2014). "However, the proportion of lymph node pDC that was BrdU+ increased significantly at day 14 post infection in both groups, reflecting the influx of recently divided pDC to lymph nodes that occurred regardless of TLR7 and TLR9 blockade." (PMID 23935491, 2013). "In contrast to IFN-α, massive numbers of TNF-α-producing cells were present in lymph nodes at both day 14 and 56 post infection, regardless of TLR7 and TLR9 blockade, with 25 to 30% of all cells in the paracortex and parafollicular cortex expressing this cytokine." (PMID 23935491, 2013). "Interestingly, unlike many of the previous studies involving herpesvirus activation of TLR signaling in pDCs, infection with UV-inactivated KSHV did not result in upregulation of IFN-α, indicating that TLR9 actually recognizes KSHV DNA upon infection of pDCs." (PMID 23061052, 2012). "Two TLRs, TLR4 and TLR9, were both observed to be expressed differentially upon separate infection with F4ab and F4ac ETEC, while no TLRs expressed differentially after F18ac ETEC infection." (PMID 22823589, 2012). "Moreover, MEFs isolated from wild-type, TLR-9−/−, TLR-3−/−, MAVS−/− and MyD88−/− and TRIF−/− C57BL/6 mice embryos were all producing similar levels of IFN-β upon MVMp infection, indicating that neither TLRs nor RLRs are involved in the IFN response triggered by replicating MVMp in MEFs." (PMID 37111493, 2023). "The trafficking of TLR9 in JIMT-1 CD44-/CD24- non-CIC population showed a similar pattern as ArLa non-CIC: The receptor was found in the ER and at low levels in endosomes in non-infected cells and upon infection TLR9 was upregulated and trafficked from the ER to the endosomes." (PMID 21079774, 2010).